Y_RNA (Y RNA )
Gene: Miscellaneous RNA gene on chromosome 5 (180,909,838 to 180,909,927, forward strand). Ensembl gene ENSG00000222852.
Homologues: Orthologues: chimpanzee Y_RNA (100% identical), guinea pig Y_RNA (57% identical). Paralogues in human: Y_RNA (83% identical), RNY4 (82% identical), RNY4P10 (82% identical), RNY4P6 (81% identical), RNY4P7 (81% identical), RNY4P9 (81% identical), Y_RNA (81% identical), RNY4P14 (80% identical), RNY4P19 (80% identical), RNY4P24 (80% identical), RNY4P25 (80% identical), RNY4P3 (80% identical), and 90 more.